NLRP3 (NLR family pyrin domain containing 3)
Diseases named in the same sentence as NLRP3 in open-access papers (continued):
Sharing a sentence is not in itself a finding about the gene and the disease.
diabetes (continued). "In addition, curcumin was found to (i) improve diabetes/chronic cerebral hypoperfusion (CCH)-induced cognitive deficits, (ii) attenuate neuronal cell death, (iii) suppress neuroinflammation induced by microglial activation, and iv) reduce NLRP3-dependent pyroptosis." (PMID 39940319, 2025). "We propose that Bif-1 regulates the activation of NLRP3 inflammasomes and is also involved in the anti-inflammatory mechanisms of CAN, which may provide new ideas for the treatment of patients with infectious pneumonia, particularly those concurrent with diabetes." (PMID 35418866, 2022). "Our in vitro study confirmed that empagliflozin reduced the activation of NLRP3 and the expression of pyroptosis-related inflammasomes in pancreatic β cells under a high glucose environment, suggesting that the NLRP3/caspase-1/GSDMD pathway may be a potential therapeutic target for diabetes." (PMID 34823419, 2021). "Despite studies that have demonstrated that NLRP3 contributes to renal ischemia reperfusion (I/R) injury by a direct effect on renal tubular epithelium, it remains unclear how NLRP3 is able to sense redox changes, particularly in renal tubular epithelium during ischemia AKI in diabetes." (PMID 27867451, 2016). "Subgroup analyses showed that the post-ACS upregulation of NLRP3, caspase-1, and IL-1β was consistent across STEMI and NSTEMI presentations and was not significantly modified by diabetes status." (PMID 41598157, 2025). "In a mice model of spontaneous non-obese diabetes, activation of NLRP3 promotes the proliferation, differentiation, and transport of diabetic TH1 cells to islets, thereby delaying the onset of diabetes." (PMID 35647057, 2022). "But there remain some problems, though DCM is a common clinical complication in patients with diabetes, there are few studies about the mechanism between DCM and pyroptosis, and the mechanism of how to activate NLRP3 is still not clear too." (PMID 35355717, 2022). "Since the lack of NLRP3 prevented DM-induced cardiac changes, we tested next whether NLRP3 inhibition could reverse diabetes-induced cardiac electrical disturbances." (PMID 27882934, 2016). "In order to determine whether NLRP3 may be responsible for the phenotypic changes in macrophages under diabetes, a GEO database GSE183698 was used to analyzed gene profile from mouse macrophages with or without NLRP3 depletion (NLRP3KO, WT)." (PMID 36405726, 2022). "Interestingly, it has been clarified that diabetes further worsened cardiac function and increased HF by promoting the activation of AIM2 and NLRC4 inflammasomes, but not NLRP3 inflammasome." (PMID 35464402, 2022). "NLRP3 inflammasomes mediate many non-infectious factor-induced inflammations such as lipid accumulation, hyperglycemia-induced oxidative stress, and hyperlipidemia, which are involved in the etiology of a variety of diseases, including NAFLD, obesity, diabetes mellitus and cardiovascular disease." (PMID 38095642, 2023).
Sepsis (543 papers, 2011 to 2026). Sepsis is defined as life-threatening organ dysfunction caused by a dysregulated host response to infection. "The activation of the NLRP3 inflammasome is a pivotal step in hyperinflammation in sepsis; however, the regulatory mechanisms underlying its activation are not fully understood." (PMID 41480749, 2026). "In Clostridium septicum infections—capable of causing sepsis and gas gangrene—NLRP3 activation is triggered by α-toxin binding to glycosylphosphatidylinositol (GPI)-anchored proteins on immune cell membranes." (PMID 40959087, 2025). "TIMP2 protects against sepsis-associated acute kidney injury by cAMP/NLRP3 axis-mediated pyroptosis." (PMID 40989844, 2025). "Transcriptomic integration revealed activation of critical signaling pathways, including NFκB/NLRP3, associated with sepsis-induced immune dysregulation." (PMID 40699828, 2025). "Emerging evidence implicates NLRP3 inflammasome activation in sepsis-associated multiorgan dysfunction." (PMID 41256846, 2025). "In vivo, emodin confers significant protection in sepsis models, with these protective effects being lost in NLRP3-deficient mice or upon macrophage-specific deletion of FUNDC1." (PMID 40520006, 2025). "The interaction between thioredoxin‐interacting protein (TXNIP) and NLRP3 is crucial for inflammasome activation and participates in inflammatory responses associated with sepsis." (PMID 40264381, 2025). "The activation of the NLRP3 inflammasome is implicated in the pathogenesis of various inflammatory conditions, for example sepsis, leading to significant elevations in IL-1β, IL-18, and caspase-1 levels." (PMID 40918153, 2025). "SIRT3, a mitochondrial deacetylase, emerges as critical in sepsis-induced lung injury, where its loss disrupts Parkin-mediated mitophagy, fueling NLRP3 inflammasome activation via mtROS and mtDNA leakage." (PMID 41026942, 2025). "Genetic silencing or pharmacological inhibition of HK2 was found to be linked to the modulation of NLRP3 activation and lipid droplet aggregation in microglial cells of sepsis." (PMID 40086696, 2025). "Subsequently, myeloid‐specific STING‐deficient mice were generated, and reduced NLRP3 activation was observed in the lung tissue of STING‐deficient mice after sepsis induction." (PMID 40211890, 2025). "As a damage-associated molecular pattern (DAMP), mtDNA exacerbates inflammatory responses in sepsis by activating the NLRP3 inflammasome and triggering pyroptosis, causing the death of alveolar macrophages and alveolar endothelial cells." (PMID 40918090, 2025). "In the context of sepsis, pathogen-associated molecular patterns (PAMPs; e.g., LPS) and damage-associated molecular patterns (DAMPs) are potent activators of the NLRP3 inflammasome in immune and muscle cells." (PMID 41334559, 2025). "Numerous studies have proven that the activation of the NLRP3 inflammasome is associated with sepsis‐associated organ damage." (PMID 40766788, 2025). "GABARAP deficiency impairs mitochondrial homeostasis in macrophages and enhances mitochondrial ROS generation, hence exacerbating NLRP3 inflammasome-dependent inflammatory responses and contributing to critical pathogenic processes in sepsis." (PMID 40781631, 2025). "Separately, macrophage migration inhibitory factor (MIF), a proinflammatory cofactor of NLRP3, antagonizes mitophagy in sepsis-associated acute kidney injury (SA-AKI)." (PMID 41026942, 2025). "Aberrant NLRP3 activation has been implicated in sepsis-associated organ dysfunction, including encephalopathy, cardiomyopathy, and lung injury, with excessive activation exacerbating inflammation and leading to tissue damage and organ failure." (PMID 40918153, 2025). "Complementarily, Zhang reported that in a mouse model of sepsis, YTHDF1 can inhibit pyroptosis of cells and alleviate the damage caused by sepsis by promoting the ubiquitination of NLRP3 and upregulating the WW domain-containing E3 ubiquitin ligase 1 (Wwp1)." (PMID 41341492, 2025).
Sepsis (continued). "Beyond inflammation, NLRP3 contributes to sepsis-associated coagulopathy by inducing tissue factor expression and phosphatidylserine externalization—mechanisms that initiate coagulation and microthrombus formation." (PMID 40558557, 2025). "Recent studies have shown the key role of NLRP3/caspase-1/GSDMD-dependent pyroptosis signaling pathway in the regulation of sepsis-associated organ dysfunction." (PMID 40708650, 2025). "Ongoing research into optimizing these systems will likely lead to improved treatment modalities for inflammatory diseases associated with NLRP3 activation, including sepsis." (PMID 40599085, 2025). "To investigate the influence of BBR on pyroptosis during sepsis‐induced acute gastric injury, we evaluated markers linked to NLRP3 activation and pyroptosis." (PMID 39484787, 2024). "In the present study, we found that METTL14 knockdown alleviated lung injury via inhibiting NLRP3 inflammasome activation in macrophages, consistent with the result in sepsis-associated myocardial dysfunction." (PMID 38218935, 2024). "Evidence supporting the efficacy of IL-1β inhibition in sepsis has predominantly been derived from NLRP3-deficient models." (PMID 39056754, 2024). "The NLRP3/caspase-1 pathway-induced pyroptosis has also been linked to cognitive impairment following sepsis." (PMID 38665289, 2024). "The NLRP3/Caspase/GSDMD signaling pathway of sepsis‐induced ALI in mice caused by pyroptosis was assessed by real‐time quantitative PCR, enzyme‐linked immunoadsorption assay, western blot analysis, PI staining, and flow cytometry." (PMID 38501547, 2024). "ERBB2IP can also mitigate the activation of the NLRP3 inflammasome and inhibit microglial pyroptosis, thereby reducing neuroinflammation associated with sepsis-related brain syndrome." (PMID 39444808, 2024). "The authors further showed that histone-induced NLRP3 activation in alveolar macrophages during sepsis was associated with increased TWIK2-dependent potassium efflux." (PMID 39206200, 2024). "Collectively, the persistence and dysregulation of NLRP3 inflammasome activation are common features of burn sepsis and are associated with poor prognosis." (PMID 38957662, 2024). "Numerous studies have demonstrated that NLRP3-induced IL-1β release is the main cause of the brain dysfunction following sepsis." (PMID 38665289, 2024). "Conversely, studies conducted on NLRP3 knockout mice have demonstrated that reduced IL-1β levels due to NLRP3 deficiency mitigate sepsis-induced skeletal muscle atrophy." (PMID 38338718, 2024). "High serum NLRP3 levels were associated with increased mortality rates, poor clinical outcomes, and lung injury severity in sepsis patients with ARDS." (PMID 37649483, 2023). "Rab11a deficiency in macrophages prevents sepsis-induced NLRP3 inflammasome activation and inflammatory lung Injury in mice." (PMID 37158595, 2023). "Activation of the NLRP3 inflammasome has been implicated in the pathogenesis of lung inflammation, injury, fibrosis, and coagulation disorders in sepsis patients with ARDS." (PMID 37649483, 2023). "systematically reviewed the NLRP3 inflammasome and its role in developing sepsis, and incorrect regulation of NF-κB has been associated with inflammation and autoimmunity." (PMID 36817458, 2023). "This sheds new light on the mechanisms of NLRP3 involvement in sepsis-associated acute kidney injury and provides further evidence for considering NLRP3 as a therapeutic target." (PMID 37759588, 2023). "Higher levels of NLRP3, caspase-1, and IL-1 β in the bloodstream of patients with sepsis increase the risk of mortality." (PMID 37600769, 2023). "According to our data, patients with sepsis-associated acute kidney injury had upregulated NLRP3 expression in their kidneys." (PMID 37759588, 2023). "Meanwhile, pneumonia-induced sepsis patients exhibited activation of NLRP3 inflammasome and production of the pyroptosis-associated pro-inflammatory cytokines IL-1β and IL-18." (PMID 36923408, 2023).
Sepsis (continued). "The diagnostic values of serum NLRP3 concentration for ARDS in sepsis patients were evaluated by receiver operating characteristics (ROC) analysis." (PMID 37649483, 2023). "Erbin protects against sepsis-associated encephalopathy by attenuating microglial pyroptosis via the IRE1α/Xbp1s-Ca2+ axis, and NLRP3/Caspase-1 pathway-induced pyroptosis mediates cognitive deficits in a mouse model of sepsis-associated encephalopathy." (PMID 38037161, 2023). "Nlrp3 deficiency has been reported to protect mice from excessive pro-inflammatory cytokine storm and organ damage in inflammatory conditions including sepsis." (PMID 36798132, 2023). "Pulmonary infection, APACHE II score and serum NLRP3 concentration were risk factors for patients with sepsis complicated with ARDS." (PMID 37649483, 2023). "The dysfunction of the NLRP3 inflammasome is implicated in a variety of inflammatory disorders including acute peritonitis, sepsis, and gout." (PMID 36978391, 2023). "Here, we intended to investigate the involvement of NLRP3 in lipopolysaccharide (LPS)-induced sepsis-associated acute kidney injury (S-AKI) and explore its mechanisms." (PMID 37759588, 2023). "Collectively, present results and past observations agree on the occurrence of a deficiency in NLRP3 inflammasome activation and reactivation abilities in sepsis." (PMID 38140660, 2023). "Existing studies suggest that the activation of NLRP3 inflammatory corpuscles is closely related to multiple organ damage caused by sepsis." (PMID 37249295, 2023). "Herein, we sought to determine the expression of NLRP3 in patients with sepsis-associated acute kidney injury and investigate the significance and mechanisms of NLRP3 involvement." (PMID 37759588, 2023). "A later study revealed that BRCC3 deficiency attenuates NLRP3‐associated inflammatory diseases such as peritonitis and sepsis." (PMID 37361896, 2023). "Previous studies have consistently demonstrated that Nlrp3 deficiency protects mice from lethal sepsis, which is associated with lower levels of IL-1β." (PMID 36798132, 2023). "We then analyzed the correlation of serum NLRP3 concentrations with sepsis severity and concurrent ARDS risk factors in all sepsis patients (n = 150)." (PMID 37649483, 2023). "In stefin B-deficient mice, we reported increased NLRP3 activation and mortality upon LPS-induced sepsis." (PMID 38067160, 2023). "The results showed that pulmonary infection (p=0.003), APACHE II score (p<0.001) and serum NLRP3 concentration (p=0.007) were independent risk factors for sepsis patients complicated with ARDS." (PMID 37649483, 2023). "Although Btk initiates an antiviral response by activating TLR3, Btk aggravates the cardiac dysfunction associated with sepsis by promoting the conduction of NF-κB and NLRP3 and their downstream signals." (PMID 35296647, 2022). "This canonical NLRP3 inflammasome activation has been observed to occur in a variety of myopathies, including skeletal muscle atrophy caused by sepsis." (PMID 36405697, 2022). "The over-accumulation of bacterial pro-inflammatory cytosolic LPS causes the development of sepsis in animals and fish through the activation of the NLRP3 inflammasome, the main mechanism of cytokine production." (PMID 36552254, 2022). "Dysregulation of NLRP3 inflammasome has been implicated in many human diseases, such as gout, diabetes and sepsis-related organ dysfunction and metabolic disorders." (PMID 36405697, 2022). "Experimental sepsis evoked a robust increase in the assembly of the NLRP3 complex in liver and kidney, which was associated with a subsequent increase in the cleavage of caspase-1, when compared to animals in the Sham group." (PMID 35178052, 2022). "Conversely, altered NLRP3 inflammasome activation capacity called NLRP3 inflammasome exhaustion has been described in infectious diseases such as sepsis or severe COVID-19 in association with deleterious outcomes." (PMID 36291172, 2022).
Sepsis (continued). "Studies have shown that activation of the NLRP3 inflammasome increases susceptibility to sepsis in mice and that melatonin administration reduces mitochondrial damage and inflammation in sepsis." (PMID 35620580, 2022). "In conclusion, in sepsis, there is an increase in proinflammatory cytokines in brain tissues at early stages, culminating in oxidative damage and NLRP3 activation, which is related to bioenergetic changes, causing the deposition of 8-oxoG in mtDNA." (PMID 36333747, 2022). "The pathogen-associated molecular patterns and damage-associated molecular patterns in sepsis activate NLRP3 and caspase-1 to release inflammatory cytokines such as IL-18 and IL-1β, aggravating the inflammatory response." (PMID 36032662, 2022). "Here, we demonstrated that p47phox caused ROS production in the function of GPR43 in sepsis-induced inflammatory reactions model through the activation of NLRP3 inflammasome." (PMID 34584017, 2021). "In this study, we evaluated the genetic association of NLRP3 polymorphisms with sepsis (640 patients and 769 controls) and characterized the impact of NLRP3 polymorphisms on NLRP3 expression and inflammatory responses." (PMID 34172780, 2021). "Our results provide a new understanding of the genetic effect of the NLRP3 inflammasome on sepsis pathophysiology and new approaches for risk assessment, as well as therapeutic strategies for sepsis patients." (PMID 34172780, 2021). "Mechanistic investigations in vitro were conducted to determine the impact of this functional NLRP3 polymorphism on NLRP3 transcription and sepsis-associated inflammatory responses." (PMID 34172780, 2021). "The genotypes and allelic distributions of the NLRP3 29940G>C polymorphism were consistent with the Hardy–Weinberg equilibrium in sepsis patients and healthy controls (All p > 0.05)." (PMID 34172780, 2021). "Carriers of 29940 GG/GC exhibited significantly increased NLRP3 mRNA expression compared to that of the CC genotype carriers, indicating a role of the 29940 G>C polymorphism in the susceptibility to sepsis progression by altering NLRP3 gene transcription." (PMID 34172780, 2021). "We previously published that platelets from the CLP polymicrobial sepsis model have increased platelet NLRP3 assembly/activation and was associated with lung and renal injury." (PMID 34638670, 2021). "In the present study, 640 septic patients and 769 controls were enrolled to explore the clinical relationship between the NLRP3 genetic variant 29940G>C and the susceptibility and progression of sepsis in a Han Chinese population." (PMID 34172780, 2021). "It is found that resveratrol exerts a protective effect on sepsis-associated encephalopathy by inhibiting the NLRP3/IL-1β axis of microglia." (PMID 34220338, 2021). "The data in this study indicated that the 29940 G>C polymorphism in the 3′-UTR of NLRP3 conferred susceptibility to the development of sepsis and a poor clinical outcome." (PMID 34172780, 2021). "Emerging evidence suggests that sepsis causes prolonged activation of the NLRP3 inflammasome, thereby contributing to a persistent inflammatory response and extensive cell injury, especially in innate immune cells." (PMID 34741186, 2021). "In this study, we explored the clinical relevance of NLRP3 genetic variation, rs10754558 (29940G>C), to sepsis susceptibility and progression in a Han Chinese population (640 septic patients and 769 controls) for the first time." (PMID 34172780, 2021). "Considering the location of the 29940G>C polymorphism within the 3′-UTR of the NLRP3 gene, we further examined the effect of the sepsis-associated G-to-C mutation at the rs10754558 site on NLRP3 mRNA stability." (PMID 34172780, 2021). "Nlrp3‐deficient mice showed an improved systolic and diastolic cardiac function and increased survival in sepsis." (PMID 34472725, 2021).